IQGAP1 (IQ motif containing GTPase activating protein 1)
Diseases named in the same sentence as IQGAP1 in open-access papers (continued):
Sharing a sentence is not in itself a finding about the gene and the disease.
cancer (continued). "IQGAP1 is a crucial regulator of cancer development by scaffolding and facilitating different oncogenic pathways, especially RAC1/CDC42, thus affecting proliferation, adhesion, migration, invasion, and metastasis." (PMID 37787041, 2023). "The IQ motif containing GTPase-activating protein 1 (IQGAP1) is an oncoprotein implicated in GBM and other cancers, but its mechanism(s) is incompletely defined." (PMID 37228393, 2023). "Upregulated IQGAP1 was detected in multiple cancer entities, including breast, colorectal, esophageal, gastric, head and neck, ovary, pancreases, and thyroid cancer." (PMID 36831467, 2023). "Patients with increased levels of IQGAP1 have a worse prognosis, demonstrating the prognostic value of IQGAP1 in many cancers." (PMID 36831467, 2023). "To further assess this concept, we analyzed the expression of both KSR1 and IQGAP1 transcripts in a number of publicly available transcriptomal datasets present in both the Pan-Cancer and Gene Expression Omnibus (GEO) repositories." (PMID 36791195, 2023). "Studies have shown that IQGAP1 is highly expressed in cancer and is closely related to metastasis potential." (PMID 35154449, 2022). "IQGAP1 was reported as a tumor suppressor in bladder cancer, playing a completely opposite role compared with other cancers." (PMID 36362301, 2022). "This is in agreement with the observed overexpression of IQGAP1 associated with the invasiveness of CRC, and especially in advanced carcinomas in which the invasive capability of cancer cells can be detected." (PMID 36276098, 2022). "The immunophilin FKBP51, the angiomotin AmotL2, and the scaffoldin IQGAP1 are overexpressed in many types of cancer, with the highest increase in leucocytes from patients undergoing oxaliplatin chemotherapy." (PMID 35563891, 2022). "In summary, we suggest IQGAP1 as a vital regulator on Clip170 tension polarization and cancer invasion and migration." (PMID 36209218, 2022). "The contribution of IQGAP1-mediated signaling to different stages of cancer progression is an emerging field." (PMID 36253497, 2022). "Many studies have reported that the overexpression of IQGAP1 contributes to different kinds of carcinoma." (PMID 36262887, 2022). "Fructose-1,6-bisphosphatase (FBP1), a gluconeogenesis enzyme that is often downregulated in cancer, can also directly bind to the WW domain of IQGAP1 and therefore inhibit IQGAP1-mediated ERK activation." (PMID 34439095, 2021). "IQGAP1 is involved in the trafficking of MMP14-containing vesicles to the leading structures of cancer cells." (PMID 34590580, 2021). "This review highlights the significant roles of IQGAP1 in cancer and provides a rationale for pursuing IQGAP1 as a drug target for developing novel cancer therapies." (PMID 34439095, 2021). "The IQ3 motif on IQGAP1 is required for its interaction with PI3K-AKT signaling, which mediates IQGAP1-associated cell proliferation, survival, migration, and invasion in cancer." (PMID 34439095, 2021). "Quantification of MVs shed from 2 × 107 cancer cells within 4 h showed that the RNAi‐mediated knockdowns of IQGAP1 in MDAMB231 cells dramatically inhibited MV shedding." (PMID 33473262, 2021). "Overexpression of ARF1 failed to increase p-ERK expression and cell proliferation in IQGAP1-deficient cancer cells, suggesting that IQGAP1 was essential for the biological function of ARF1 in cancer." (PMID 33408784, 2021). "Two decades of studies provide evidence that IQGAP1 plays an essential role in promoting cancer development." (PMID 34439095, 2021). "In this context, IQGAP1 often colocalizes with Rho GTPases at the leading edge of the invasive front of cancer cells." (PMID 34439095, 2021). "In this respect, an alternative strategy to disrupt oncogenic MAPK signalling in human cancers is to target scaffold protein IQGAP1, which regulates the assembly of MAPK components for pathway activation." (PMID 34822659, 2021).
cancer (continued). "IQGAP1 is highly expressed in the tumor lesions and suggested to be involved in cancer cell metastasis." (PMID 34590580, 2021). "In this review, we describe the different oncogenic pathways affected by IQGAP1, summarize the role of IQGAP1 in different types of cancer, and discuss the emerging evidence of IQGAP1 in regulating tumor immunology." (PMID 34439095, 2021). "IQGAP1 is overexpressed in several cancers including ovarian cancer, colorectal cancer, glioblastoma, lung cancer, and gastric cancer." (PMID 34925466, 2021). "Acting as a scaffolding protein for multiple key oncogenic pathways, IQGAP1 has been investigated for years as an oncogene that promotes cancer." (PMID 34439095, 2021). "Overall, the level of expression of IQGAP1 and the patterns of IQGAP1 localization within cells show clinical relevance to the prognosis of cancer patients, indicating its importance in cancer development." (PMID 34439095, 2021). "In this article, we review the different pathways regulated by IQGAP1 during cancer development, and the role of IQGAP1 in different types of cancer, including cancers of the head and neck, breast, pancreas, liver, colorectal, stomach, and ovary." (PMID 34439095, 2021). "By regulating cytoskeleton organization, IQGAP1 influences cell migration, invasion, adhesion, and metastasis during cancer development." (PMID 34439095, 2021). "We then describe clinical and molecular evidence for the contribution of IQGAP1 in different types of cancers." (PMID 34439095, 2021). "We also discuss IQGAP1′s regulation of the immune system, which is of importance to cancer progression." (PMID 34439095, 2021). "IQGAP1 is involved in many cancer-related activities, such as proliferation, apoptosis, migration, invasion and metastases." (PMID 34439095, 2021). "IQGAP1 is overexpressed in many human cancers, including HNSCCs, and regulates multiple cellular activities, including but not limited to cytoskeletal dynamics, cell proliferation, cell–cell adhesion, and invasion." (PMID 34068608, 2021). "IQGAP2 has been proposed to be a tumour suppressor and its expression is downregulated when IQGAP1 is overexpressed in hepatocellular carcinoma, while IQGAP3 shows oncogenic properties." (PMID 33672268, 2021). "IQGAP1 stimulates filopodia formation, and promotes cell motility and invasion in mammalian and cancer cells, particularly through the interaction with β-catenin, e-cadherin, and small GTPase, i.e., Cdc42, Rac1, and RhoC." (PMID 32824461, 2020). "We discuss a model in which IQGAP1 modulates centrosome-nuclear crosstalk to regulate cell division and imparts on cancer." (PMID 32655836, 2020). "IQGAP1 which has been shown to be correlated with many cancers promotes β-catenin translocation to nucleus in HepG2 cells which in turn is involved in the Wnt signaling pathway." (PMID 33062407, 2020). "IQ motif-containing GTPase- activating protein 1 (IQGAP1), a protein upregulated in multiple types of cancer, acts as a scaffold for this pathway and others implicated in cancer." (PMID 32923516, 2020). "In conclusion, like IQGAP1, a known oncogene that is overexpressed in various cancer types, IQGAP3 also has important roles in carcinogenesis, especially in cell migration and invasion." (PMID 32824461, 2020). "The results obtained from IQGAP1 mutant analysis were substantiated in TNBC cancer cell lines, using centrosome markers." (PMID 32655836, 2020). "Collectively, these data suggest that although IQGAP1 lacks the typical GTPase-activating function, the dysregulation of IQGAP1 regulation is a critical step in cancer progression for different cancer types." (PMID 32353968, 2020). "IQGAP1 is overexpressed in many human cancers, including breast, lung, colorectal cancers and HNSCCs." (PMID 32923516, 2020). "Given IQGAP1’s effects on invadopodia and extravasation, this influence is most likely to apply during invasion of cancer cells from a primary tumor and subsequent intravasation into circulation." (PMID 32051509, 2020).
cancer (continued). "After 4NQO treatment, Iqgap1-/- mice developed significantly lower cancer incidences, lesser disease severity, and fewer cancer foci per mouse, when compared to the Iqgap1+/+ mice." (PMID 32923516, 2020). "IQGAP1 expression is preferentially expressed at the invasion front, and especially in advanced carcinomas that invaded into the subserosa, suggesting a role of IQGAP1 in CRC invasion." (PMID 32178475, 2020). "GLK directly phosphorylates and activates IQGAP1, resulting in induction of Cdc42-mediated cell migration and cancer metastasis." (PMID 31640697, 2019). "In UM-SCC47 and MDA-MB-231 cells, IQGAP1WT enhanced EGF-stimulated wound closure compared to control, mock-transfected cells, whereas IQGAP1∆IQ3 had no impact, indicating that the IQ3 motif is required for the IQGAP1-mediated cancer cell migration." (PMID 31235839, 2019). "IQGAP1 acts as a scaffold to modulate important signal transduction in PI3K/mTOR/AKT and MAPK pathways and is highly associated with cancers, including HNSCC36–38." (PMID 31798960, 2019). "We found that three pathways, “Pathways in cancer” (hsa05200), “Focal adhesion” (hsa04510), and “Insulin signaling pathway” (hsa04910), are widely affected by IQGAP1 and VAV2." (PMID 31798960, 2019). "IQGAP1 is a scaffold protein that interacts with distinct proteins to regulate cancer cell proliferation and migration." (PMID 31101875, 2019). "IQGAP1 plays a role in cancer progression, whereas IQGAP2 seems to act as atumor suppressor, and IQGAP3 promotes cancer growth and metastases." (PMID 29581849, 2018). "This QC mechanism likely requires tightly regulated IQGAP1 levels, as IQGAP1 overexpression (e.g. during cancer) leads to decreased junctional strength and disrupted cell architecture." (PMID 27880081, 2018). "During T cell activation, IQGAP1 moves swiftly out of the centriole docking site, along with the actin patch, allowing docking and the release of lytic granules to the cancer cell." (PMID 27880081, 2018). "IQGAP1+ staining was observed in neurons (Map2+ cells), in cancer stem cells (CSC; nestin+) and in several macrophages (CD31+ or Iba1+)." (PMID 28098764, 2017). "IQGAP1 was detected to be highly expressed in several cancer types, and resulted in poor prognosis and survival of patients." (PMID 28282856, 2017). "The expression pattern and role of IQGAP1 has been well established in many cancers, whereas those of IQGAP2 and IQGAP3, have mostly remained unexplored." (PMID 29073199, 2017). "As an effector of CDC42, IQGAP1 can bind directly to CDC42 and has been implicated in the modulation of cell architecture and regulation of exocytosis in human cancers." (PMID 28282856, 2017). "During cancer progression, paracrine signalling emanating from cancer cells decreases IQGAP1 expression in HSCs, which promotes HSC activation into myofibroblasts as well as metastatic outgrowth." (PMID 28085225, 2017). "In other cancer cell systems, it has been shown that the active form of Cdc42 is capable of binding to IQGAP1 to increase cancer migration and carcinogenesis." (PMID 27486972, 2016). "Among these was IQ-domain GTPase-activating protein 1 (IQGAP1), a scaffold protein known to bind to Cdc42 and influence cell migration in normal and cancer cells." (PMID 27486972, 2016). "The methylation-mediated repression of miR-124 leads to the overexpression of IQGAP1, which in turn accelerates cancer cell proliferation, EMT and invasion." (PMID 26934121, 2016). "The consequences of IQGAP1 deletion on gastric epithelial cell behaviour and on the acquisition of cancer stem cell (CSC)-like properties were evaluated." (PMID 27729612, 2016). "IQGAP1 is a key mediator of cytoskeletal rearrangements and is thought to play an important role in several cancer types by stimulating cell mobility and invasion." (PMID 27264994, 2016). "This supports a model that the loss of miR-124 activates IQGAP1 and contributes to EMT and cancer cell invasiveness." (PMID 26934121, 2016).
cancer (continued). "The abnormal expression of IQGAP1 widely exists in many cancers, but biological roles of IQGAP1 cooperation with its interacting proteins to involve in tumorigenesis remain to clarify." (PMID 26252773, 2015). "Mice deficient in IQGAP were refractory to HRAS-driven carcinogenesis and depletion of IQGAP1 reduced invasion in RAS oncogene-driven cancer cells by suppression of ERK activity." (PMID 26033452, 2015). "Since cholesterol is essential for all cell types, and IQGAP1 is ubiquitously expressed, we asked if IQGAP1 targeting to cholesterol-rich lipid rafts can be detected in other cancer cells." (PMID 25924234, 2015). "The alteration of IQGAP1 expression and localization correlate with cancer progression in several human primary tumors." (PMID 26252773, 2015). "In the present research, we studied the influence of RhoC and different structures of IQGAP1 on cancer cell proliferation and cell cycle related proteins." (PMID 23145020, 2012). "Since IQGAP1 has been implicated in tumor metastasis, it will be important to determine if tyrosine phosphorylation of IQGAP1 in cancer cells has functional consequences or is a result of overactive tyrosine kinases." (PMID 22505937, 2012). "IQGAP1 also participate the regulation of cancer cell proliferation as a downstream effector of RhoC." (PMID 23145020, 2012). "Here, we survey involvement of a significantly understudied protein, IQGAP2, and its homolog, IQGAP1, in cancer with more specific emphasis on the development of HCC." (PMID 22973521, 2012). "Significant amount of evidence also implicates IQGAP1 in promoting tumorigenesis in various cancers, characterizing it as a bona fide oncogene." (PMID 22973521, 2012). "IQGAP1 has been shown to regulate cell proliferation and migration in vitro, and is overexpressed in aggressive cancers." (PMID 20977743, 2010). "IQGAP1 has been shown to cross-link actin filaments, and plays a key role in cell motility in various systems, including fibroblasts, cancer cells and ECs." (PMID 20976168, 2010). "Notably, a subset of tumor cells in control cancer samples displayed a higher IQGAP1 signal relative to CK7, hinting at a subpopulation with enhanced migratory or adhesive properties." (PMID 40868059, 2025). "Overexpressed in a broad spectrum of cancers, IQGAP1 facilitates tumor progression by interfacing with membrane-bound receptors and cytoplasmic signaling mediators, orchestrating a network of molecular interactions critical to cancer cell survival and dissemination." (PMID 41035668, 2025). "In addition, IQGAP1 regulates the cytoskeleton by modulating actin dynamics and cell motility, which is important for processes like wound healing, immune response, and cancer metastasis." (PMID 41035668, 2025). "As cancer therapies face the growing challenge of drug resistance, targeting IQGAP1 could offer a novel strategy for overcoming this hurdle." (PMID 41035668, 2025). "IQGAP1 mediates the Wnt/β-catenin signaling pathway, promoting cancer metastasis." (PMID 41035668, 2025). "Beyond cancer and immunity, IQGAP1 has shown relevance in metabolic disorders." (PMID 41035668, 2025). "This dual regulatory role positions IQGAP1 as a key mediator of MET-driven cancers." (PMID 41035668, 2025). "The role of IQGAP1 in cancer has garnered significant attention." (PMID 41035668, 2025). "As mechanistic insights deepen and novel targeting strategies mature, IQGAP1-based interventions may emerge as powerful tools in addressing unmet clinical needs across cancer, metabolic disorders, immune dysregulation, and beyond." (PMID 41035668, 2025). "Because many types of cancer overexpress IQGAP1 and/or depend on signaling through IQGAP1, therapies that target IQGAP1 and its related signaling may be helpful once we understand how IQGAP1 works in cancer." (PMID 38546389, 2024). "The migration of cancer cells is influenced by the IQGAP1 protein." (PMID 38374934, 2024).
cancer (continued). "By constructing various signaling complex scaffolds, IQGAP1 aids in the progression of cancer." (PMID 38546389, 2024). "We thus aim to study whether the overexpressed IQGAP1 in CGN c.3560 C > T cancer cells affects the activities of the Rho family." (PMID 38424547, 2024). "Notably, IQGAP1 exhibits increased expression at both the mRNA and protein levels across various cancers that correlate with aggressiveness." (PMID 38424547, 2024). "Although some studies suggested that IQGAP1 was not frequently mutated in cancer apart from HNSC, the results of this study indicated that IQGAP1 exhibited high mutation rates in USEC, SKCM, COAD, STAD, BLCA, CESC, and LUSC." (PMID 38584831, 2024). "New roles for IQGAP1 in cancer signal transduction have been discovered over the past ten years." (PMID 38546389, 2024). "Like EGFR, increased IQGAP1 expression has also been found in a variety of cancers." (PMID 39357822, 2024). "Coupling of EGF/EGFR to Akt by IQGAP1 has implications in cancer." (PMID 37071417, 2023). "In addition, IQGAP1 is known to mediate the Wnt/β‐catenin signaling pathway to induce cancer metastasis." (PMID 37635636, 2023). "Thus, preliminary studies targeting IQGAP1 are encouraging to expand upon the distinct roles of IQGAPs in physiology and cancer." (PMID 37488602, 2023). "Furthermore, IQGAP1 appears to be an exceptionally attractive therapeutic target because it acts as a hub for signaling pathways involved in cancer progression." (PMID 35785216, 2022). "The interaction between Cdc42 and IQGAP1 enhances migration and invasion of cancer cells." (PMID 36253497, 2022). "Moreover, intracellular processes involved in cell differentiation, cell proliferation, and cancer transformation are influenced by IQGAP1 interactions with external signals." (PMID 36276098, 2022). "Cancer development may be influenced by IQGAP1, as this factor controls numerous cellular processes relevant to cancer development." (PMID 36559011, 2022). "Further, although there are no mutations, several cancer types exhibit an unusually high expression of IQGAP1." (PMID 36559011, 2022). "IQGAP1 is hypothesized to contribute to the changed cancer cell phenotype by modulating signaling pathways involved in cell proliferation and transformation, cell-cell adhesion weakening cell motility and invasion stimulation." (PMID 34925466, 2021). "Although further work is necessary to fully characterise this complex network, the IQGAP1-Hippo module could potentially be targeted for cancer therapy, especially in HCC." (PMID 33672268, 2021). "High levels of expression of IQGAP1 in cancer correlates with poorer prognosis for patients." (PMID 34439095, 2021). "IQGAP1 promotes cancer progression by scaffolding different signaling complexes." (PMID 34439095, 2021). "Our results also help to shed light on the physiological relevance of IQGAP1 in cancer." (PMID 33672268, 2021). "Interestingly, some studies highlighted the reciprocal expression pattern of IQGAP1/IQGAP2 in cancers, hinting at tight regulation of one isoform over another." (PMID 33846302, 2021). "A1-mediated altered translation has been implicated in cellular proliferation and cancer, where growth factor receptors and oncogenes like FGF-2 (fibroblast growth factor 2), MYC (c-Myc), IQGAP1 (IQ motif containing GTPase activating protein 1), and CYLD (cyclin D1) are aberrantly translated." (PMID 34439945, 2021). "Overexpression of IQGAP1 might contribute to constitutive activation of wnt signaling and thus leads to cancer progression." (PMID 33062407, 2020). "With these activities, IQGAP1 promotes tumorigenesis and is upregulated in numerous cancer types." (PMID 33266355, 2020). "Altogether, these findings suggest that IQGAP1 plays an important role in the centrosome by which it controls cell proliferation and that it may impact cancer development." (PMID 32655836, 2020).